CD63 (CD63 molecule)
Diseases named in the same sentence as CD63 in open-access papers (continued):
Sharing a sentence is not in itself a finding about the gene and the disease.
prostate carcinoma (26 papers, 2012 to 2026). A carcinoma that arises from epithelial cells of the prostate gland. "Furthermore, soluble GPI-80 in the conditioned medium was associated with the exosome marker CD63 and was also detected in the plasma obtained from prostate cancer patients." (PMID 34769456, 2021). "The most effective antibody to capture prostate cancer-derived exosomes was anti-CD63; hence, this was used in further experiments." (PMID 38400284, 2024). "The most effective antibody to capture prostate cancer-derived exosomes was anti-CD63 and, thus, it has been used in further experiments." (PMID 38400284, 2024). "These stable cell lines were used for these tests since they are most often used for prostate cancer EV research, and they have been shown to express high levels of CD63 in EV." (PMID 37175677, 2023). "Most of the exosomes from prostate cancer cells were round, with typical saucer-like structures, a diameter of approximately 40–160 nm, and the specific molecular markers CD63 and tgs101 were expressed on the exosome membrane." (PMID 35941539, 2022). "Previous studies have shown the value of exosomal CD9 and CD63 for the prostate cancer diagnostics in blood and urine." (PMID 35204378, 2022). "While the expression and subcellular localisation of tetraspanin EV markers CD9 and CD63 are distinct in prostate cancer, the effect of androgens such as DHT and ENZ on the S‐EVs profile is unclear." (PMID 34434533, 2021). "Biotinylated anti-EpCAM, anti-ITGA3 or anti-CD63 antibodies were applied for capturing EVs from cell culture supernatants of the prostate cancer cell lines LNCaP, DU145 and PC3 and one of the control cell line HEK293." (PMID 31296879, 2019). "Herein, we have optimized a quantitative high throughput screen (qHTS) assay to identify compounds that modulate exosome biogenesis and/or release by aggressive prostate cancer (PCa) CD63-GFP-expressing C4-2B cells." (PMID 29802284, 2018). "We evaluated this assay system with exosomes isolated from culture supernatants of prostate cancer cell line PC3 using anti-CD63 antibody and anti-CD9 antibody." (PMID 26082068, 2012). "Moreover, colocalization experiments using prostate cancer cell-derived EVs confirmed that MB-targeted RNAs such as miR−141 co-localised with the exosomal marker CD63, supporting the biological relevance and detection specificity of the TCLN platform." (PMID 41340217, 2025). "CD63, a surface marker of EVs, is upregulated in various carcinomas, including prostate cancer." (PMID 39075471, 2024). "A theranostic antibody designed to specifically detect PSMA helps to further differentiate between circulating S‐EVs from prostate cancer patients, for both CD9 and CD63 captured S‐EVs, providing enhanced potential to assess heterogeneity of S‐EVs for prostate cancer diagnosis." (PMID 34434533, 2021). "Transplantation of CD63-Antares2-expressing prostate cancer cells into mice allowed determining the amount of cancer-derived exosomes released from primary tumors into the bloodstream and visualizing the long-term homing behavior of exosomes to their target organs or tissues." (PMID 33024173, 2020). "Additionally, we found SSX2 is expressed in a CD45−/EpCAM+/CD63+ cell subset in the blood of patients with prostate cancer, a cell subset specifically representing prostate-specific circulating tumor cells." (PMID 27276714, 2016). "Moreover, ExoScreen allowed sensitive detection of exosomes in human serum from healthy donors and prostate cancer patients using anti-CD63 antibody and anti-CD9 antibody." (PMID 26082068, 2012). "The aim of the current study was to analyze CD63, CD9, and MMR protein expression in prostate tissue in patients with prostate cancer and benign hyperplasia and its correlation with ISUP grade groups and progression-free survival." (PMID 35204378, 2022). "However, CD63 and CD9 expression in the tissue of prostate cancer and benign hyperplasia is still poorly understood." (PMID 35204378, 2022).
prostate carcinoma (continued). "In urine-derived EVs (CD63-labeled vesicles), both TMPRSS2-ERG and a prostate cancer biomarker, Prostate Cancer Antigen (PCA-3) mRNA, were found, indicating that the mRNA composition of EVs is informative and may give prospective prostate cancer biomarkers." (PMID 36059497, 2022). "Interestingly, DHT treatment leads to increased cell surface area and the appearance of filopodia on the cell surface and expression of EV markers CD63 and CD9 on the cell surface of prostate cancer cells." (PMID 34434533, 2021). "In the CD63-CD63 assay, the expression of CD63 was relatively similar among the EVs of the prostate cancer cell lines (data not shown)." (PMID 31296879, 2019). "To assess whether CD9 EV can serve as biomarker in prostate cancer, we examined the level of CD9 positive and CD63 positive EV in prostate cancer in plasma derived from prostate cancer patients (n=6) and benign prostate hyperplasia (BPH) patients (n=10)." (PMID 28881726, 2017). "In urine, the level of CD9 positive and CD63 positive EV have been shown to be higher in men with prostate cancer, as well as in plasma, supporting the clinical utility of CD9 positive EV measurement in patients biofluids for men with prostate cancer." (PMID 28881726, 2017). "Manipulation of the AR signalling axis alters the protein cargo in S‐EVs in LNCaP prostate cancer cells, and that the tetraspanin CD9 has been shown to be significantly more abundant in EVs from DHT‐treated cells when comparison with other S‐EVs markers including: TSG101, Alix, CD63 and CD81." (PMID 34434533, 2021). "This notion was further supported by our finding that prostate CAFs but not prostate cancer cells express a higher level of the TIMP-1 receptor, tetraspanin CD63." (PMID 24143225, 2013).
glioblastoma (25 papers, 2015 to 2025). The most malignant astrocytic tumor (WHO grade IV). "To investigate the association between CD63 and immune cells, we performed automated quantitative double-immunofluorescence on ten glioblastomas." (PMID 29523123, 2018). "Significant results were also observed for TNC+/CD81+ in newly diagnosed and relapsed patients (FC =5.9 and 6.4, respectively), as well as for TNC+/CD63+ (FC = 10.96 in newly diagnosed glioblastoma; p < 0.001)." (PMID 40056466, 2025). "Although newly diagnosed glioblastoma had the highest plasmafold changes for TNC+/CD63+ EVs than HD, weakor insignificant differences were found for this subpopulation inrecurrent patients compared to HD and post-OP subjects." (PMID 40056466, 2025). "We first isolated EVs from patient serum and compared them to EVs from control subjects and found a significant increase in protein levels of the EV marker CD63 in glioblastoma patient sera compared to control sera." (PMID 37568598, 2023). "Over expression of CD63 protein as measured by immunohistochemistry was previously observed in glioblastomas and its role in stemness was suggested." (PMID 32042278, 2020). "We further found that total counts of double positive FASN+/CD63+ as well as FASN+/CD81+ EVs were significantly increased in the blood of glioblastoma patients, and the former was also significant in patients with anaplastic astrocytomas." (PMID 32178271, 2020). "The expression of CD63 was widely distributed in astrocytomas with a significantly increased level in glioblastomas." (PMID 29523123, 2018). "In anaplastic astrocytomas and glioblastomas, the expression patterns of CD63 appeared similar, however, perinecrotic areas and proliferative blood vessels only expressed CD63 in glioblastomas." (PMID 29523123, 2018). "The proximity ligation assay showed TIMP-1 and CD63 proteins in close molecular proximity revealing these interacting molecules as red spots in the tumor cells of the glioblastoma biopsies." (PMID 29523123, 2018). "In contrast to the considerable variation observed in the TIMP-1 expression in glioblastomas, the variation in the CD63 expression was minor, and virtually all tumor cells were positive." (PMID 29523123, 2018). "Using the TCGA dataset, glioblastomas with the highest CD63 levels had a significant upregulation and downregulation of several genes compared to glioblastomas with the lowest levels." (PMID 29523123, 2018). "The amount of CD63+ tumor cells was similar in diffuse and anaplastic astrocytomas, while the amount was significantly higher in glioblastomas (p < 0.001)." (PMID 29523123, 2018). "We found a grade-dependent increase in CD63 expression with glioblastomas having significantly higher levels compared to diffuse and anaplastic astrocytomas (p < 0.001); also IDH wildtype tumors had significantly higher CD63 levels compared IDH mutated tumors." (PMID 29523123, 2018). "Further, CD63 was found to interact with TIMP-4, and CD63/TIMP-4 co-expression was associated with poorer outcome in glioblastoma patients." (PMID 29523123, 2018). "The level of CD63+ blood vessels tended to be lowest in anaplastic astrocytomas followed by diffuse astrocytomas, while glioblastomas had the highest score (p < 0.001 and p < 0.01, respectively)." (PMID 29523123, 2018). "In conclusion, we found an increased expression of CD63 in glioblastomas as well as a weak correlation between CD63 and TIMP-1." (PMID 29523123, 2018). "Altogether, these results suggest that TIMP-1 is a stronger prognosticator in glioblastoma patients compared to CD63 and TIMP-4." (PMID 29523123, 2018). "Using double-immunofluorescence, we showed that TIMP-1 and CD63 were co-expressed in some glioblastoma cells." (PMID 29523123, 2018). "Looking at the total CD63 score, 74% and 71% of the diffuse and anaplastic astrocytomas were in the lowest CD63 expression group, while this was only the case for 55% of the glioblastomas." (PMID 29523123, 2018).
glioblastoma (continued). "In summary, these assays suggest that TIMP-1 and CD63 are located closely together and interact in glioblastomas." (PMID 29523123, 2018). "We detected CD63+ tumor cells in the majority of the tumors and found a significantly higher CD63 expression in glioblastomas compared to diffuse and anaplastic astrocytomas." (PMID 29523123, 2018). "List of differentially up- and downregulated genes in the group of glioblastomas with the highest CD63 mRNA levels compared to the group of glioblastomas with the lowest CD63 mRNA levels." (PMID 29523123, 2018). "The present study for the first time describes an increased expression of CD63 and increased expression/ secretion of P-selectin in a homogeneous cohort of first diagnosed glioblastoma patients." (PMID 29899827, 2018). "Comparing the total CD63 score, glioblastomas had significantly higher score compared to diffuse and anaplastic astrocytomas (p < 0.001)." (PMID 29523123, 2018). "Finally, we analyze glioblastoma clinical samples and assess the total (tEGFR) and aEGFR fractions in CD63 EVs." (PMID 38830977, 2024). "In metastatic carcinoma and glioma cells, TIMP1 has been demonstrated to interact with P75NTR, TIMP-1, and CD63, and may play a role in glioblastoma stemness." (PMID 37091145, 2023). "Since we barely detected CD63-positive sEVs in supernatants of our glioblastoma cells in preliminary experiments, we focused our examinations on the expression of CD9 and CD81 in human glioma tissues using accessible online data and in the different glioblastoma cells." (PMID 36203458, 2022). "Tetraspanin markers are commonly used to identify EVs and we previously demonstrated that the number and proportion of CD63+ circulating plasma EVs is significantly elevated in patients with glioblastomas and anaplastic astrocytomas, with a similar trend for CD81+ EVs." (PMID 32178271, 2020). "Also, CD63 expression did not affect the prognostic potential of TIMP-1 suggesting that TIMP-1 is a more valuable prognostic marker in glioblastomas compared to CD63 alone or in combination with CD63." (PMID 29523123, 2018). "CD63+ tumor cells were present in all anaplastic astrocytoma and glioblastoma samples, while CD63+ blood vessels were detected in 93% of the anaplastic astrocytomas and 99% of the glioblastomas." (PMID 29523123, 2018). "For the percentage of CD63+ tumor cells, tumor cell intensity, the percentage of CD63+ blood vessels, and CD63 blood vessel intensity, the highest scores 2 and 3 were most frequently given to glioblastomas, whereas the lowest score 1 was most often given to diffuse and anaplastic astrocytomas." (PMID 29523123, 2018). "Whether CD63 plays a role in glioblastoma invasion needs further investigation." (PMID 29523123, 2018). "Whether TIMP-1 and CD63 can interact on the surface of glioblastoma cells is so far unknown." (PMID 29523123, 2018). "Serum exosomes were analyzed in patients with glioblastoma, and results of a previous study revealed that EGFR, EGFRvIII and CD63 were expressed at high levels." (PMID 40612948, 2025). "The lipid profiles of glioblastoma have demonstrated elevated FASN in glioma tissue and, specifically, in extracellular vesicles (EVs), including CD63- and CD8-positive glioblastoma EVs." (PMID 38539424, 2024). "Immunostaining is accomplished with fluorescent antibodies against EV markers such as CD9, CD63, and CD81 or cancer markers, in this particular study from three glioblastoma cell lines overexpressing EGFRvIII, EGFR, or IDH1‐R132." (PMID 35898167, 2023). "They applied the designed assay to detect glioblastoma biomarkers CD-pan (CD9, CD63, and CD81), with EGFR, EGFRvIII and GAPDH as control markers, from supernatants of glioblastoma cells." (PMID 33276535, 2020). "The present study suggests that CD63 is highly expressed in glioblastomas and that TIMP-1 and CD63 interact." (PMID 29523123, 2018).
glioblastoma (continued). "CD63 and CD148 are highly abundant on certain cell types including the glioblastoma cell lines LN229 and T98G, and CD29 (even though detected on nearly every cell type) and CD142 are generally found at the lower end of the detected abundance range." (PMID 25894527, 2015). "We have also shown that expression of CD63 and TIMP‐1 appears to be correlated with glioblastoma." (PMID 37081824, 2023). "Furthermore, in glioblastoma, the co-expression of TIMP-1 and stem cell markers, as well as the expression of CD63, has suggested a role for TIMP-1 and CD63 in cancer cell stemness." (PMID 37443843, 2023). "It further showed that only the total number of CD63+ EVs but not CD81+ EVs was increased in patients with glioblastomas and malignant astrocytomas." (PMID 32178271, 2020). "Importantly, however, the total count of double positive FASN+/CD63+ EVs (mean 4.1 × 105/mL GBM vs 5.8 × 104/mL HD, P = 0.001) as well as the total count of FASN+/CD81+ EVs (mean 8.0 × 105/mL GBM vs 2.3 × 105/mL HD, P = 0.007) was significantly increased in the plasma of glioblastoma patients." (PMID 32178271, 2020). "In addition, co-expression of CD63 and TIMP1 have also been shown in patients with glioblastoma and astrocytoma by the other group." (PMID 30222750, 2018). "Co-expression of TIMP-1 and stem cell markers as well as the wide expression of CD63 might suggest a role for TIMP-1 and CD63 in glioblastoma stemness." (PMID 29523123, 2018). "In a previous study, we showed that TIMP-1 was a significant prognostic marker in glioblastomas, and in the present study we aimed to further investigate the role of TIMP-1 in glioblastomas by focusing on the potential TIMP-1 interacting protein CD63." (PMID 29523123, 2018). "A significant correlation was found between TIMP-1 and CD63, and the TIMP-1 and CD63 proteins were co-expressed at the cellular level and located in close molecular proximity, suggesting that TIMP-1 and CD63 could be co-players in glioblastomas." (PMID 29523123, 2018). "Whether tumor stem-like cells in glioblastomas express CD63 has not been investigated directly in the present study as CD63 was expressed by virtually all tumor cells in the glioblastomas." (PMID 29523123, 2018).
lung carcinoma (24 papers, 2014 to 2026). "CD63, a universal marker of exosomes in combination with PD-L1, is known to cause a worse response to immunotherapy, and when applied to clinical specimens, it has demonstrated exceptional capabilities in diagnosing and staging lung cancer." (PMID 39459055, 2024). "The EFIRM method was utilized for the analysis of exosomal profiles in mice injected with human lung cancer H640 cells, a cell line engineered to express the exosome marker human CD63-GFP." (PMID 41573685, 2025). "A lateral flow aptamer assay targeting the CD63 membrane protein of exosomes has been developed for the detection of lung cancer." (PMID 39459055, 2024). "Knockdown of UBA6 induced the increased expression of CD63 in H1975 and other lung cancer cells, including H1299 and A549." (PMID 38474091, 2024). "Untilthis moment, QCM-D and SPR studies on lung cancer cell-derived EVsfocused mainly on CD63 detection.29−31 The proposed protocolwas validated for its specificity, limit of detection (LOD), and limitof quantification (LOQ)." (PMID 37307147, 2023). "In lung cancer cells for example, proliferation is regulated through the Kras–Erk–NF-kB–Timp1–CD63–FAK–Erk loop: activation of the cellular proliferation process through this pathway requires Timp1 and its receptor CD63, and Timp1 is the target gene for NF-kB." (PMID 38023152, 2023). "Our mouse model was injected with human H460-hCD63-GFP lung cancer cells, which subsequently produced species-specific CD63 proteins and GAPDH mRNA, the very markers we detected and reported in blood and saliva." (PMID 25397880, 2014). "In order to study exosome function secreted by lung cancer cells, we first extracted exosomes from serum by overspeed centrifugation method, and identified exosomes extracted by exosome markers Alix and CD63, which were verified by projection electron microscopy and Western blot." (PMID 33627047, 2021). "Furthermore, EVs isolated with anti-CD61 beads enclosed mRNA expression patterns that might be associated to early-stage lung cancer, in contrast with EVs captured through CD9, CD63 or CD81." (PMID 35933395, 2022). "This study applied SPR and QCM-D to studythe concentration of EVs using three well-defined tetraspanin biomarkers(CD9, CD63, and CD81) in lung cancer cells." (PMID 37307147, 2023). "Western blotting analysis of 10K and 100K pellets in lung cancer cell lines was based on CD9 and CD63 as markers of small EVs (exosomes), and BiP and Annexin A1 as markers of large EVs (oncosomes)." (PMID 32634139, 2020). "As anti‐TNC antibody‐functionalized nanopillars enrich cancer‐associated sEVs, we expected DECODE to provide an sEV molecular profile with higher expressions of CD63, THBS2, VCAN, and TNC in the three lung cancer cell lines and low/negligible biomarker expression from HBECs and PBS controls." (PMID 36394090, 2022). "By applying targeted mass spectrometry with stable isotope-labeled peptide standards, we assessed the levels of 28 EV-associated proteins, including the conventional exosome markers CD9, CD63, CD81, CD82, and HSPA8, in vesicles derived from the lung cancer cell lines NCI-H23 and A549." (PMID 34684727, 2021). "In any case, cancer patients presented, in general, higher CD63+-CD81+ signal than non-cancer donors, in line with previous observations in lung cancer patients compared with healthy donor plasma." (PMID 36726591, 2022).